SQSTM1 (sequestosome 1)
Diseases named in the same sentence as SQSTM1 in open-access papers (continued):
Sharing a sentence is not in itself a finding about the gene and the disease.
cancer (continued). "To survey the relevance of SQSTM1 expression levels to ER stress responses in cancers, we analyzed RNA expression levels of SQSTM1 and 16 transcription factors (TFs), known to be involved in ER stress-regulated gene expression, as a signature of ER stress." (PMID 40396020, 2022). "Our novel approach aims to convert the autophagic receptor function of SQSTM1 for cancer cell survival to the formation of CASP aggresomes for cancer cell death in conjunction with irradiation." (PMID 40396020, 2022). "We postulate that aberrant UPR signaling, often seen in cancer cells, upregulates SQSTM1 expression and autophagic flux among other dysregulation of cellular processes." (PMID 40396020, 2022). "Our recent study proposes small-molecule ligands of SQSTM1 as a therapeutic tool to convert survival autophagy to apoptotic cell death in ER-stressed and apoptosis-resistant cancer cells." (PMID 40396020, 2022). "Expressions of MAP1LC3B and SQSTM1 have been widely used to evaluate autophagy status in mammalian cells and their clinical significance in cancer patients." (PMID 34829743, 2021). "The role of p62 (also known as sequestosome 1/SQSTM1) is multifaceted in cancer biology and includes a role in regulating the NF-κB signaling pathway." (PMID 33859932, 2021). "The silencing of either NRF2 or p62/SQSTM1 with specific siRNA demonstrated the crosstalk between the two molecules and that the knockdown of either molecule increased the cancer cell sensitivity to Zn(II)–curc-induced cell death." (PMID 33669070, 2021). "To further expand the observation of DNA autophagic inhibition to cell activity, we screened a series of human cancer cells with immunofluorescence double-staining of cGAS and SQSTM1, and HCT116, 786-0, PC3M, and DU145 cells were screened." (PMID 34123836, 2021). "Matching with our observations, elevated SQSTM1 levels have strongly been indicated to be involved in resistance to platinum-based cancer therapy." (PMID 33673611, 2021). "The accumulation of MAP1LC3B and SQSTM1 plays a different role in clinicopathological outcomes and prognosis in various types of cancer." (PMID 34829743, 2021). "The other orthologous would compensate their function while silencing MAP1LC3B or/and SQSTM1 in cancer cells." (PMID 34829743, 2021). "Knockdown of autophagic genes involved in mitochondrial clearance, including BNIP3L/Nix and SQSTM1/p62 also sensitizes cells to mitochondria-targeted therapies, arguing that these genes promote cancer cell survival." (PMID 33883040, 2021). "Previous studies demonstrated that MELK interacts with and phosphorylates its downstream substrates including FOXM1, eukaryotic translation initiation factor 4B (eIF4B) and SQSTM1, and thus promotes the malignant phenotype of human cancer." (PMID 32047721, 2020). "A study has reported that the p62/SQSTM1 accumulation is required for resveratrol-induced autophagic cell death in cancer cells." (PMID 32882870, 2020). "Phosphorylation of p62/Sqstm1 at Ser349 enhanced the tolerance of cells to anti-cancer drugs and proliferation potency via the activation of the transcription factor Nrf2." (PMID 33260729, 2020). "In this State‐of‐the‐Art Review, we discuss about diverse roles of p62/SQSTM1 and about their deregulation in cancer." (PMID 30499183, 2019). "A human p62-encoding plasmid was originally proposed as a classic DNA vaccine eliciting adaptive immune response against the p62/SQSTM1 protein over-expressed in cancer cells." (PMID 31754084, 2019). "By means of TWAS, we recovered seven genes (APOC1, APOE, BIN1, HMGB1, PRKAA1, SQSTM1, and UCP2) significantly associated to AD traits and some cancer models." (PMID 31608105, 2019). "In this study, we found that EGFR TKIs, including gefitinib and AZD9291, impaired lysosome-dependent degradation of SQSTM1, thus compromising their anti-cancer efficiency." (PMID 31637005, 2019).
cancer (continued). "Altogether our findings highlight the regulation of mitophagy and SQSTM1/p62 protein as therapeutic strategies in cancer." (PMID 31547522, 2019). "Elevated levels of SQSTM1 have been demonstrated in oncogenesis and resistance to cancer chemotherapy." (PMID 31311202, 2019). "One of the key proteins involved in and regulated by autophagy is SQSTM1, which is a critical new player in cancer." (PMID 30782064, 2019). "LC3 was mainly expressed in the cytoplasm of the cancer cells, while p62/SQSTM1 was expressed in both the nucleus and cytoplasm." (PMID 30925913, 2019). "In contrast, silencing TRIB3 decreases the basal and IGF‐1‐induced accumulation of SQSTM1 in cancer cells." (PMID 27038142, 2016). "This work provides the proof‐of‐concepts for targeting the TRIB3/SQSTM1 interaction as a therapeutic strategy against cancers, especially in T2D patients with cancers." (PMID 27038142, 2016). "Analysis of human tissues revealed progressive accumulation of p62/SQSTM1 in a significant proportion of cancer samples compared to normal tissue, suggesting that defective autophagy has relevance to SCCHN." (PMID 24599075, 2014). "Our data, therefore, support a model in which accumulation of p62/SQSTM1 in SCCHN cancers promotes resistance to PI3K pathway inhibitors." (PMID 24599075, 2014). "But we found S100A7, CHCHD2 and SQSTM1 directly interacted with Akt that plays a vital role in signalling pathway of cancer cells." (PMID 24991204, 2014). "Human p62 (also known as SQSTM1 for sequestosome 1) is a multidomain adaptor protein involved in various diseases including cancer." (PMID 23950728, 2013). "Sequestosome 1 (SQSTM1/p62), long established as a selective autophagy receptor and ubiquitin-binding scaffold, is now recognized as an emerging regulatory hub that integrates signaling, metabolism, and stress adaptation in cancer." (PMID 42021865, 2026). "Moreover, the probability of gene dependency for SQSTM1, which estimates the reliance of cancer cells on a particular gene, also correlates with the aneuploidy score of cancer cells." (PMID 40527892, 2025). "SQSTM1 is an important marker protein in autophagy, playing several roles in autophagy regulation, with researchers finding that reducing SQSTM1 expression could significantly affect autophagy activation in cancer cells." (PMID 41154776, 2025). "Similarly, in our study, knocking down ALKBH5 increased the expression of ABCA1 and decreased autophagy substrate SQSTM1, which activated autophagy-related pathways for anti-cancer effects." (PMID 38481816, 2024). "In cancer, mitochondrial autophagy experiences impairment, affecting mitochondrial autophagy receptors and adapters, including PINK1, Parkin, BNIP3, BNIP3L/NIX, and p62/SQSTM1, along with associated signaling pathways." (PMID 38505747, 2024). "With regard to the opposite roles in cancer cells, p62/SQSTM1 is thought to be a Janus." (PMID 38398629, 2024). "PSMD14 could enhance cancer cells malignancy through the LRPPRC/Beclin1-Bcl-2/SQSTM1 signaling pathway inducing autophagy." (PMID 36632137, 2023). "Some studies have explored the roles of SLC7A11, CAPG, and SQSTM1 in cancer." (PMID 37198416, 2023). "The combination of GLUL and SQSTM1 inhibitors in precisely characterized patients may have superior effects against cancer compared to immunotherapy alone." (PMID 38149248, 2023). "In addition, genes encoding for functional products involved in autophagy regulation after iron-intake (i.e., sequestosome 1 (SQSTM1)) exhibited under-expression in cancer cells while they were up-regulated in PNT2 cells." (PMID 36829917, 2023). "Therefore, p62/SQSTM1 and LC3 are universally used together as the hallmark of autophagic flux in cancer studies." (PMID 36104717, 2022). "SQSTM1/p62 also plays an important role at the crossroads of autophagy, apoptosis, and cancer." (PMID 36248994, 2022).
cancer (continued). "Although the role of p62/SQSTM1 in tumourigenesis is context dependent, it may be an important pharmacological target for regulating TGFβ signalling transduction in cancer." (PMID 36267157, 2022). "Downregulation of SQSTM1-expression has been reported in JQ1-resistant cancer cell lines." (PMID 36231049, 2022). "FusionGDB analysis reveals 33 different Sqstm1 fusion genes in various cancers and diseases." (PMID 35814476, 2022). "SQSTM1, a protein involved in mitophagy, was upregulated after 1,25(OH)2D treatment, suggesting a selective and adaptive process to remove dysfunctional mitochondria from cancer cells." (PMID 35079680, 2022). "In contrast, in bulk analysis of the MDA-MB-231 and cisplatin-treated PACCs, most of the proteins showed similar abundances at the same injection amount (1.0 μg) level; however, we found more than two-fold decrease in PACC compared to MDA-MB-231 cancer cells for p62/SQSTM1, HIST1H4A and HIST1H1E." (PMID 35810282, 2022). "Analysis was not performed for other types of cancer (including LIHC) in that the sample sizes with Sqstm1 mutation of these cancers are not powerful enough." (PMID 35814476, 2022). "The inhibition of autophagy through chemical inhibitors as well as the genomic silencing of cGAS or SQSTM1 could suppress the growth and survival of cancer cells, and induced DNA damage could increase the sensitivity to these inhibitors." (PMID 34123836, 2021). "This switch may be evolutionarily conserved and not only cancer related and probably is a consequence of the activation of Nrf2 by the autophagy adaptor p62/SQSTM1." (PMID 35052602, 2021). "It is noteworthy that the phenomenon of LC3B-II and SQSTM1 accumulation observed in CB-2-treated A549 cells could also be detected in other cancer cell types, suggesting that CB-2 may have a universal inhibitory effect on autophagy." (PMID 34440609, 2021). "p62/SQSTM1 is frequently up-regulated in many cancers including hepatocellular carcinoma." (PMID 33854041, 2021). "In the cancer cell lines analyzed, Zinc–curcumin Zn (II)–curc compound can also display anticancer effects via diverse molecular mechanisms, including markedly increasing heme oxygenase-1 (HO-1) p62/SQSTM1 and the Nrf2 protein levels along with its targets." (PMID 35011412, 2021). "To determine the source of the increased number of autophagosomes mediated byIL-6 treatment, we examined the levels of free GFP (GFP protein freed from the fusion protein GFP-LC3B upon autophagic flux enhancement) and SQSTM1 (p62) expression in cancer cells transfected with a GFP-LC3B plasmid." (PMID 34131122, 2021). "SQSTM1 has been reported as a potential oncogene in various cancers, including HCC." (PMID 32807131, 2020). "Literatures showed that targeting autophagy-related proteins LC3, ATG5, ATG7, SQSTM1, and Akt/mTOR (mammalian target of rapamycin) pathway could regulate autophagy initiation in cancer cells." (PMID 31309361, 2019). "SQSTM1/p62 is related to autophagy and can be chosen as a novel cancer antigen." (PMID 30678689, 2019). "SQSTM1 regulates autophagy and apoptosis and acts as a signaling hub, which regulates cell viability in response to cytotoxic stress, thus playing a vital role in cancer." (PMID 31311202, 2019). "Our results suggested that MAP1LC3B and SQSTM1 may modulate autophagy for cancer development, malignancy and relapse in a subsite-dependent manner." (PMID 30477228, 2018). "Silencing SQSTM1 inhibited cancer cell invasion in BMSCC cells." (PMID 30477228, 2018). "p62 (SQSTM1) is thought to be another critical protein that targets other proteins for proteasome degradation or autophagic digestion, at the crossroads of autophagy, apoptosis and cancer." (PMID 26802026, 2016). "However, these researchers found that TRIB3 overexpression inhibits LC3‐I/‐II conversion and increases the level of both soluble and insoluble SQSTM1 in cancer cells." (PMID 27038142, 2016).
cancer (continued). "However, the difficulty of cellular uptake has hindered A2 to exert its interrupting the TRIB3/SQSTM1 interaction in cancer cells." (PMID 27038142, 2016). "Taken together, these results support the hypothesis that autophagy competence and p62/SQSTM1 could be used to stratify certain cancers for their response to specific therapies." (PMID 24599075, 2014). "The findings that SCCHN display increased p62/SQSTM1 expression compared to normal and dysplastic tissue suggests that these findings are clinically meaningful and that there are many cancers that will be inherently resistant to PI3K inhibition due to defects in autophagy." (PMID 24599075, 2014). "This interaction between p62/SQSTM1 and Nrf2 could be leveraged to improve cancer therapy outcomes." (PMID 39456414, 2024). "Sequestosome-1, which is also called p62, is a multidomain, multifunctional protein, which is involved in autophagy, defense against oxidative stress via activation of the Keap1/Nrf2 system, protein aggregation and sequestration, and apoptosis for different types of cancer cells." (PMID 36673375, 2023). "Similarly, knockdown of SQSTM1/p62 produced an evident anti-cancer effect in vivo." (PMID 37373349, 2023). "Therefore, the knockdown of MAP1LC3B or/and SQSTM1 might result in a defective autophagy, thus protecting cancer cells." (PMID 34829743, 2021). "Thus, in situations with altered levels and localization of SQSTM1/p62 expression, such as osteoclasts in Paget’s disease of bone and various cancers, SQSTM1/p62 may compartmentalize Ajuba and thereby impact its cellular functions and disease pathogenesis." (PMID 34735553, 2021). "High p62 levels promote the activation of NRF2, which in turn induces the transcriptional activation of the p62/SQSTM1 gene, further increasing p62 accumulation through a feed-forward loop, and, therefore, p62 can be considered a key pro-oncogenic regulator to be targeted in anti-cancer therapy." (PMID 33669070, 2021). "Additionally our results may have implications for cancer states, where increased SQSTM1/p62 and Ajuba levels have been observed and have many key roles in cellular fate." (PMID 34735553, 2021). "Autophagy may also protect against cancer via suppression of oxidative stress via modulation of nuclear factor erythroid 2-related factor 2 (Nfe2l2/Nrf2)/kelch-like ECH-associated protein 1 (Keap1) and SQSTM1/p62 pathway." (PMID 33224954, 2020). "In the autophagy mediated by copper and erastin (a ferroptosis inducer), the autophagy receptors TAX1BP1 and SQSTM1 can promote the degradation of GPX4, effectively reducing the resistance of cancer cells to ferroptosis." (PMID 41323827, 2025). "Positive feedback between SQSTM1 and NRF2 therefore has an important function in cancer development and progression." (PMID 39941813, 2025). "LC3, SQSTM1 and ATG5 in cancer tissues are closely related to cancer aggressiveness and prognosis, and are often used as independent prognostic markers for cancer." (PMID 37776538, 2024). "The NEDD4-1 can also involve in the phagophore elongation and substrate selection in cancer cells through interaction with LC3 and the autophagy receptor SQSTM1." (PMID 36918822, 2023). "Finally, SQSTM1/p62 may act as a shielded factor in cancer cell survival by triggering autophagy and blocking apoptosis under drug-induced stress; otherwise, it may act as a driving force to determine the adverse fate of tumor cells via mechanisms that remain partially unclear." (PMID 37373349, 2023). "Following Ru-bdcurc treatment, cancer cells greatly increased the NRF2 protein levels and the expression of NRF2 targets, including HO-1, NQO1, and p62/SQSTM1, suggesting the induction of NRF2 transcriptional activity." (PMID 36831129, 2023). "In contrast, the autophagy receptor sequestosome 1 (SQSTM1, best known as p62) is required for the elimination of SLC40A1 to promote iron-dependent ferroptosis in cancer cells in vitro and in vivo." (PMID 36845736, 2023).
cancer (continued). "Several mitophagy adaptors, such as a parkin, PINK1, bifunctional mitochondrial protein (BNIP3), autophagic indicator (P62/SQSTM1) and signaling pathways (nuclear factor (erythroid-derived 2)-like 2 (Nrf2)/PINK1/Parkin pathway), are impaired in cancer." (PMID 37375256, 2023). "P62/SQSTM1, LC3 and Beclin‐1 are critical proteins involved in the overall process of autophagy and function in cancer development." (PMID 37665055, 2023). "From the aspects of cancer grading and Spearman correlation analysis, we provided a brief summary of RELA and SQSTM1, which emphasized their importance in HCC with ROC curve plotted to evaluate the reliability of our analyses." (PMID 35456457, 2022). "In contrast, the coefficients of SQSTM1, HSP90AA1, and STMN1 were positive, which was consistent with the reported function of promoting or suppressing cancer, indicating that DRGPI is a valuable prognostic biomarker for HCC patients." (PMID 35892599, 2022). "We then, from the aspects of cancer grading and Spearman correlation analysis, provided a brief summary of RELA and SQSTM1 to show their importance in HCC." (PMID 35456457, 2022). "Three categories of cancer cells—cells with high cGAS and SQSTM1 (786-0 and PC3M), low cGAS and SQSTM1 (HeLa and HCT116), and high SQSTM1 but low cGAS (DU145)—were selected." (PMID 34123836, 2021). "In vivo, in a leukemia cell line (NB4) xenograft model treated with the anti-cancer agent selenite, tumors show a reduction of LC3-II and an increase of p62/SQSTM1, which is indicative of autophagy inhibition." (PMID 32232004, 2020). "Furthermore, it examines the molecular mechanism by which the autophagy receptors TAX1BP1 and SQSTM1 induce GPX4 degradation and impair cancer cell resistance to ferroptosis during copper‐ and erastin‐mediated autophagy processes." (PMID 41323827, 2025). "p62/SQSTM1 and LC3 are used together as markers of autophagy in cancer research." (PMID 37175359, 2023). "SQSTM1 is required for STING1-dependent autophagy to inhibit M. tuberculosis infection in macrophages, but SQSTM1 is dispensable for STING1-mediated autophagy in HeLa cancer cells." (PMID 35371032, 2022). "This suggests that the crosstalk between p62/SQSTM1 and NRF2 could be therapeutically exploited to increase cancer patient response to therapies." (PMID 33669070, 2021). "The compounds were reported to be non-cytotoxic towards cancer cells, however, based on the observed upregulated level of SQSTM1/p62 in the treated cells, the authors suggested that the compounds are capable of autophagy inhibition." (PMID 32967369, 2020). "However, the puncta of both MAP1LC3B-II and SQSTM1 were very rare in all tissues of our TMA, likely due to the different cancer types or tissues that we used." (PMID 30477228, 2018). "Therefore, they conclude that the TRIB3/SQSTM1 interaction mediates the IGF‐induced the SQSTM1 accumulation, which compromises UPS as well as autophagic degradation in cancer cells." (PMID 27038142, 2016). "Notably, the anti‐tumor activity of phloridzin was due to the Pleiotropic suppression of proteins such as P62/SQSTM1 and LC3 І/II in the JAK/STAT signaling pathway, which is responsible for oesophagal cancer growth, metastasis, and apoptosis, thus affecting the overall development of cancer cells." (PMID 40761486, 2025). "Additionally, there is limited research exploring the direct link between EMT and SQSTM1, but some studies have suggested that SQSTM1 may play a role in the EMT process in cancer cells." (PMID 38370394, 2024). "Cancer cells treated with proteasome inhibitors also upregulate autophagy and knockdown of two proteasomal ubiquitin receptors, PSMD4/S5a and ADRM1, in HeLa cells promotes compensatory SQSTM1/p62-mediated autophagy that clears accumulated polyubiquitinated substrates." (PMID 32887506, 2020). "Nevertheless, the correlation of SQSTM1 with detailed subsites of cancers has never been reported." (PMID 30477228, 2018).